SPRY2 (sprouty RTK signaling antagonist 2)
Diseases named in the same sentence as SPRY2 in open-access papers (continued):
Sharing a sentence is not in itself a finding about the gene and the disease.
cancer (continued). "Finally, by considering the genes recapitulating IL-3 biological functions, we proposed a model, including IL-3Rα, SNAI1, ZEB1, VIM, CTNNB1, MMP2, SPRY2, and CD274, that remarkably discriminates cancer aggressiveness (AUC = 0.86 95% CI = 0.82–0.89)." (PMID 36010912, 2022). "Besides SPRY2 promoter plays an important role in ERK signaling and inhibition of several human cancers 43,44." (PMID 34764329, 2021). "SPRY2 and miR-194-dependent suppression of AKT2 and other repressors of E-cadherin may account for upregulation of E-cadherin and inhibition of cancer cell migration and invasion." (PMID 26434583, 2016). "Consistent with expectations, canonical luminal genes such as ESR1, GATA3, FOXA1, TFF1 and IGF1R were higher in ER+ samples compared to triple negative samples, while proliferation and mesenchymal genes such as SPRY2, SNAI2, FOSL1, MET and BUB1 were higher in triple negative cancers." (PMID 24520381, 2014). "When the nonuniform expression patterns of Spry1 and Spry2 across the cancer cell lines were individually compared against this pattern, nonconformity was found." (PMID 23251157, 2012). "In sum, our observation revealed nonuniform expression patterns of Spry1 and Spry2 across the seven cancer cell lines, with the expression levels ranging from almost nil to high." (PMID 23251157, 2012). "SPRY2 expression in cancer cell lines was inversely correlated with the IC50 values of all MEK inhibitors for the cancer cell lines with ρs ranging from − 0.24 to − 0.43 (all p-values <4E-08), indicating that cancer cell lines with higher SPRY2 expression are more sensitive to the MEK inhibitors." (PMID 33858332, 2021). "It has been widely established that miR-21 promotes survival and proliferation of cancer cells by directly inhibiting its targets, including PTEN, Programmed Cell Death 4 (PDCD4), reversion-inducing-cysteine-rich protein with kazal motifs (RECK), and sprouty RTK signaling antagonist 2 (SPRY2)." (PMID 34066762, 2021). "Our results also revealed that SPRY2 expression is positively correlated with the sensitivity of the cancer cell lines to many MEK inhibitors from GDSC, suggesting that SPRY2 expression may be a predictive biomarker for the effectiveness of MEK kinase inhibitors." (PMID 33858332, 2021). "SPRY2 downregulation by siRNA resulted in trans-differentiation of cancer cells and significantly shifted cell morphology from fibroblastoid or more-elongated fibroblast-like shape to epithelial-like shape in both cell lines irrespective of the endogenous level of SPRY2 expression." (PMID 26434583, 2016). "We found that following Spry2 overexpression, miR-21 was no longer able to enhance EGF-induced cancer cell proliferation or phosphorylation of ERK1/2 and AKT." (PMID 30464258, 2018).
infection (2 papers, 2014 to 2023). The state of being infected such as from the introduction of a foreign agent such as serum, vaccine, antigenic substance or organism. "Two well-known targets of miR-21 and miR-146a, transforming growth factor beta-1 (TGFB1) and sprouty homolog 2 (SPRY2), were already found downregulated in THP1 cells during early infection." (PMID 37424776, 2023).
adenocarcinoma (1 paper, 2021). A common cancer characterized by the presence of malignant glandular cells. "Increased SPRY2 expression was even more evident in adenocarcinomas compared to that of healthy colonic mucosa." (PMID 34685612, 2021). "For the first time, SPRY2 hypomethylation was identified in adenocarcinomas in the promoter and gene body." (PMID 34685612, 2021). "Furthermore, we also found an increase in SPRY2 transcripts in adenocarcinomas compared to adjacent control colon samples from two separate data sources: GEO (GSE166427) and TCGA, respectfully." (PMID 34685612, 2021).
cardiac disease (1 paper, 2013). "In cardiac disease, functional assessment of miR-21 implicates PDCD4, SPRY1 or SPRY2, Phosphatase and tensin homolog, and Fas ligand as the major targets of miR-21." (PMID 23441172, 2013).
metabolic disease (1 paper, 2019). A congenital disorder (due to inherited enzyme abnormality) or acquired (due to failure of a metabolically important organ) disorder resulting from an abnormal metabolic process. "We have shown that SPRY2 KO increases glucose uptake and lipid droplet accumulation in HepG2 cells, and leads to downstream transcriptomic changes in genes relevant to metabolic diseases." (PMID 31664995, 2019).
neurodevelopmental disorder (1 paper, 2024). A behavioral and cognitive disorder with onset during the developmental period that involves impaired or aberrant development of intellectual, motor, or social functions. "Alterations in the expression or mutations of SPRY2 proteins can disrupt signaling cascades, leading to neurodevelopmental disorders." (PMID 39456824, 2024). "Furthermore, this review highlights the possible role of SPRY2 in neurodevelopmental disorders, as well as its future therapeutic implications." (PMID 39456824, 2024). "In conclusion, SPRY2 is an effective regulatory protein of the FGF/VEGF/EGF/BDNF signaling pathway and could be targeted as a therapeutic molecule in neurodevelopmental disorders." (PMID 39456824, 2024).
neurological diseases (1 paper, 2021). "Conversely, in mice, SPRY2 promoter hypomethylation was associated with SPRY2 upregulation and could have implications as a driver of neuronal impairment involved in neurological diseases such as Alzheimer’s." (PMID 34685612, 2021).
psychiatric disease (1 paper, 2014). "As for the psychiatric disease variants we identified as targets of Δphotoperiod-driven selection, the two for MDD show different patterns: the risk allele frequency increases with Δphotoperiod for GPHN and decreases for NDFIP2/SPRY2." (PMID 25358694, 2014).
SPRY2 also shares sentences with these, for which no sentence is quoted: non-small cell lung carcinoma (4 papers); Hypertension (3); chronic lymphocytic leukemia (2); inflammatory bowel disease (2); lung cancer (2); rhabdomyosarcoma (2); skin cancer (2); ulcerative colitis (2); acute myeloid leukemia (1); Alzheimer disease (1); autism (1); benign prostatic hyperplasia (1); Bladder (1); brain cancer (1); brain tumor (1); Burkitt lymphoma (1); clear cell sarcomas of the kidney (1); colon adenocarcinoma (1); diffuse large B-cell lymphoma (1); endometrioid adenocarcinoma (1); fibrosarcoma (1); hepatic cirrhosis (1); Hepatic steatosis (1); intrahepatic cholangiocarcinoma (1); kidney tumors (1); liver cirrhosis (1); liver diseases (1); lung adenocarcinoma (1); lymph node metastasis (1); macroglossia (1).
A further 10 diseases each share a sentence with SPRY2 in 1 paper.